CTLA4 (cytotoxic T-lymphocyte associated protein 4)
Diseases named in the same sentence as CTLA4 in open-access papers (continued):
Sharing a sentence is not in itself a finding about the gene and the disease.
tumor (continued). "CTLA-4 inhibitors interfere with the interaction of CTLA-4 and B7 to erase the suppressive impact of CTLA-4 on T-cell activity and promote antitumor immune response, leading to tumor regression." (PMID 36849435, 2023). "CTLA4-CAR T cells promoted IL-2 and IFN-γ secretion and suppressed tumor growth in xenograft models of malignant B cells." (PMID 37457699, 2023). "The model is constructed to describe the interactions between tumor populations, virus population, tumor-specific CTL response, NK cells, virus-specific immune populations, tumor suppressive cytokine IFN-γ, and the effect of immune checkpoint inhibitor CTLA-4." (PMID 36766849, 2023). "This subset also expressed higher CTLA-4 (both in the periphery and NT) and LAG-3 (at the tumor site) than the CD28− counterpart." (PMID 37898752, 2023). "ICI monotherapies induced the expansion of different tumor-infiltrating T cells (TILs), i.e., PD-1 blockade expanded exhausted-like CD8+ CTLs, whereas CTLA-4 blockade expanded both ICOS+ Th1-like CD4 effectors and exhausted CD8+ CTLs." (PMID 37928556, 2023). "Single agent anti-PD-1 or anti-CTLA-4 increased the infiltrating ICOS+ CD4+ T cells to a similar degree, but combination blockade interestingly had a greater effect on the percentage of tumor-infiltrating lymphocytes (TILs) composed of ICOS+ CD4+T cells." (PMID 37449205, 2023). "The expression levels of immune checkpoint genes, including CTLA4, CD96, and TIGIT, were also enriched in the first layer (0–250 μm) on the tumor side, indicating an elevated immunosuppressive status of immune cells in this area." (PMID 37337030, 2023). "This involved analyzing the gene expression of CTLA-4 and serum levels IGF-1 in peripheral blood cells and sera to detect the tumor's responsiveness to the targeted therapy trastuzumab." (PMID 38406785, 2023). "Blocking immune checkpoint molecules, which allows T cells to proliferate and kill the tumor cells, has achieved considerable success in clinical treatment for LUAD patients, especially the use of PD-1 and CTLA-4 inhibitors." (PMID 36983658, 2023). "Previous study showed tumor dampened the immune response and immunotherapy by making use of immune checkpoint genes, including PD1, PD-L1 and CTLA4." (PMID 37388242, 2023). "We found that PD1 blockade alone was sufficient to reduce tumor growth in the MC38 model, while treatment with both anti-PD1 and anti-CTLA4 was required to inhibit growth of B16F10 tumors." (PMID 36394642, 2023). "Oncolytic VACVs expressing CTLA-4 inhibitors and GM-CSF elicited robust systemic CD8+ T-cell-dependent anti-tumor immunity and long-lasting anti-tumor immunity by expanding peripheral effector CD8+ T-cells and reducing Tregs and exhausted CD8+ T-cells." (PMID 38283361, 2023). "Experimental studies on rats suggest the efficacy of a DNA vaccine targeting CTLA-4 and PD-1, while other studies focus on developing mRNA vaccines for CCA targeting tumor antigens (CD247, TRRAP, FCGR1A)." (PMID 37376451, 2023). "Both LAG-3 and CTLA-4 can inhibit TCR signaling pathway, thus resulting in immune tolerance of tumor cells." (PMID 37484526, 2023). "In tumor-bearing mice, combination therapy with both toosendanin and ICI (PD-1 and CTLA-4 blockade) outperformed toosendanin or ICI administered alone, slowing tumor growth and improving median survival." (PMID 38132354, 2023). "With anti-CTLA-4, the PRCC values of δc and αy, with respect to the tumor size are P^(δc)=−0.5613, and P^(αy)=−0.5270, respectively, while with single dose of OVT, the corresponding PRCC values are P(δc)=−0.4167, and P(αy)=−0.4054, respectively." (PMID 36766849, 2023). "Low malignant 67NR or highly malignant 4T1 tumor-bearing mice were treated with either the multi-kinase inhibitor sorafenib or immune checkpoint inhibitors (ICI, combination of anti-PD1 and anti-CTLA4)." (PMID 37221619, 2023). "We found tumor-infiltrating T-cells (CD4, CD8), TAMs, MDSCs, and immune checkpoints including PD1, Lag3, and CTLA4 in C0321 tumors." (PMID 37901240, 2023).
tumor (continued). "A major study comparing investigational antibodies to CTLA-4, PD-1, PD-L1, and PD-L-2 found that the combination of anti-PD-L1 and CTLA-4 was the most effective, with a 75% tumor-free survival rate in mice." (PMID 36980182, 2023). "ICIs blocked inhibitory immune checkpoints such as PD-1, PD-L1, and CTLA-4 to reboot the cancer-immunity cycle (CIC) and prevent tumor immune evasion, thus restoring and maintaining anti-tumor immunity." (PMID 36875059, 2023). "And ILC3 depletion obviously impaired the effectiveness of anti-PD-1 and anti-CTLA-4 therapy in CRC, indicating that ILC3 operates as an essential protective agent for ICB immunotherapy to exert effective anti-tumor effects." (PMID 37122757, 2023). "Proinflammatory cytokines (TNF-α, IL-β, and IL-23) released by M2-type TAMs in solid tumors continue induce overexpression of PD-L1, CTLA4, and glucocorticoid-induced TNF receptor family-regulated protein (GITR) to inhibit tumor immunity." (PMID 37880233, 2023). "Combination of ICBs (including anti-PD-L1, anti-PD-1 and anti-CTLA-4) and MK2206 significantly inhibited tumor growth in 4T1, B16-F10 and mGSC cell lines and prolonged survival in B16-F10 and mGSC cell lines." (PMID 38110614, 2023). "Bacteroides fragilis and Bacteroides thetaiotaomicron govern the efficacy of CTLA blockade therapy in tumor patients, since FMT from human to mice confirms the positive correlation between B.fragilis and CTLA-4 responses." (PMID 37936694, 2023). "Therefore, this study aimed to investigate the effect of the visceral adipose tissue secretome from OGJ patients with both early- and late-stage tumours, on T cell phenotypes and whether addition of PD-1, PD-L1 or CTLA-4 ICBs might enhance an anti-tumour T cell phenotype." (PMID 36790524, 2023). "Beyond PD-1/PD-L1 and CTLA-4, LAG-3 has emerged as a novel tumor immunotherapy target as an indication of tumor prognosis." (PMID 37803407, 2023). "PD-1 and CTLA-4 interactions with their natural ligands, PD-L1 and CD80/CD86, respectively, promote tumor growth through multiple mechanisms including T cell anergy and apoptosis." (PMID 37359554, 2023). "aimed to evaluate the tumor growth response to PI3K inhibitors, PTX, anti-CTLA-4 antibody, and anti-PD-1 antibody treatment." (PMID 37860188, 2023). "Below, we focus on inhibitory checkpoints regulated by PD-1/PD-L1, CTLA-4, and CD47 that suppress innate and adaptive immune cells including APCs and effector T cells that orchestrate tumor immunity." (PMID 37958404, 2023). "Longitudinal BLI data indicated CD4+ T cell–dependent efficacy of combined IL-6 and CTLA-4 blockade, as CD4+ T cell–depleted mice receiving therapeutic Abs had accelerated tumor growth progression compared with mice receiving only the combination therapy." (PMID 36881480, 2023). "More established immune markers need to be investigated, such as interferon-gamma, CTLA-4 and CD28, to further characterize the tumor immune microenvironment." (PMID 37175905, 2023). "We analyzed the expression of PD-L1, CD8, CTLA-4 and IFN-γ in the tumor and regional lymph node (LN) of patients with GC and compared it with clinical and pathological data." (PMID 36979688, 2023). "Checkpoint receptors such as PD1 /PD-L1 and CTLA4 can be blocked to relieve CD8+ T cells exhaustion and restart prime, respectively, thereby eradicating tumor cells that express antigens (Farhood, Najafi & Mortezaee, 2019)." (PMID 37180585, 2023). "Increasing evidence reveals a tumor cell-intrinsic expression of immune receptors, including the CD28 family member CTLA-4 as well as other checkpoint receptors like LAG3, TIGIT, and PD-1 in various malignancies." (PMID 37259155, 2023). "It has been shown that inhibiting TGF-β signaling reduces the number of Tregs and restores the tumour sensitivity to anti-PD-1 and anti-CTLA-4 therapy, and blocking TGF-β prior to radiotherapy increases clonogenic cell death and decreases tumour growth." (PMID 38259489, 2023).
tumor (continued). "In combination with blocking Abs against inhibitory (PD1, CTLA4) and agonists against activatory (GITR, 4-1BB, ICOS, OX40) immune checkpoints, the anti-tumor response was potentiated." (PMID 37686465, 2023). "CTLA-4 is highly expressed on activated and exhausted CD4 T cells, Tregs, activated and exhausted CD8 T cells, and in some tumor cells." (PMID 37427115, 2023). "The gene expression profile in CMS3 TME of KRASmut shows upregulation of CD40, CTLA4, ARG1, STAT3, IDO, and CD274, making it a key regulator of immune suppression in TME regions surrounding the KRASmut tumor." (PMID 36831441, 2023). "In addition, interference with the expression of RAP2C-AS1 suppresses the proliferation and migration of BLCA cells, and RAP2C-AS1 could affect the expression of CD274 and CTLA4, which could serve as prognostic markers and characterize the tumor microenvironment in BLCA." (PMID 38071230, 2023). "Moreover, the expression of immune response target factors, such as CTLA-4,B7-H1,B7-H3,B7-H4 and PD-1 on the surface of tumor cells and effector T cells can be negatively regulated by these immunosuppressive factors and cells, resulting in tumor cells immune escape." (PMID 37803307, 2023). "An orthotopic B.C. transplanted tumor model in mice with humanized immune systems was constructed, in which the Role of CHI3L1/MAF/CTLA4 in the immune escape of TNBC was explored." (PMID 37838657, 2023). "For example, CTLA4, STAC3, TBC1D10C and TNFSF13B were found to show weaker correlation with KIR (Killer Cell Immunoglobulin-like Receptor) family genes in tumor condition." (PMID 37908350, 2023). "LAG-3 staining of lymphocytes was observed in 43 baseline tumor specimens (81%, n = 43/53) of patients treated with combination anti-LAG-3 + anti-PD-1 ± anti-CTLA-4 immunotherapy." (PMID 37808404, 2023). "In tumors, PD-1 or CTLA-4 is expressed on CD8+ T cells and binds to PD-L1 or CD80/CD86 expressed on tumor cells and tumor-infiltrating myeloid cells (e.g., TAMs), respectively." (PMID 37345660, 2023). "Priming is a crucial step in boosting anti-tumor immune responses with treatments such as anti-CTLA-4 antibodies and is a known contributor to the increased sensitivity of the CT26 tumor model to immunotherapy, as it is a self-priming model." (PMID 37920465, 2023). "When combined with CTLA-4 ICB treatment (150 μg of anti-CTLA-4/mice), the tumor was significantly suppressed and eventually eliminated." (PMID 36987269, 2023). "Specifically, the expression levels of immune checkpoint genes CTLA4 and PDCD1 (the gene coding for PD-1) were significantly increased in the low PIDG score group, suggesting an active immune state and a stronger anti-tumor immune response." (PMID 38136994, 2023). "The binding of CTLA-4 to CD80/CD86 or PD-L1 to PD-1 suppresses T-cell activation, impairing tumour immune response and promoting a tolerogenic tumour microenvironment (TME)." (PMID 37460712, 2023). "A promising strategy to overcome these hurdles is simultaneously co-blockade of two cancer antigens, for example, CTLA-4 and PD-1, preferentially in the TME by BsAbs, restricting immune responses specific to the tumor site." (PMID 37441075, 2023). "Anti-CTLA4 and anti-PD1 therapies and their combined usage have resulted in an effective tumor response by reactivating T-lymphocytes." (PMID 37568785, 2023). "In the present investigation, while PDL1 and PDL2 expression in the tumor group was lower than that in the normal group, the expression of TIGIT, CTLA4, LAG3, and PD1 in the tumor group was higher than that in the normal group." (PMID 37266661, 2023). "Existing data in dual therapy (anti-CTLA-4 + anti-PD-1) also demonstrated the importance of CD4+ and CD8+ T-cell recruitment in the anti-tumor effect." (PMID 35433707, 2022). "Among those secretory factors, IDO was found to be overexpressed in tumor, mediate immune escape by reducing both tumor-infiltrating CD8+ T cells and B cells, and contribute to the resistance of anti-CTLA-4 therapy." (PMID 36324128, 2022).
tumor (continued). "A recent study showed that anti-CTLA-4 immunotherapy combined with peripheral targeted radiotherapy resulted in impaired anxiety and cognitive functions associated with neuro-inflammation and microglial activation in mice, but the mechanisms linking tumor and immunotherapy are not understood." (PMID 36513991, 2022). "We showed that tumor-Ag-specific CD8 T cells at the tumor site, which expressed the ICs PD-1, TIGIT, CTLA-4, and TIM-3, as well as CD39, are at an advanced effector memory (CD45RA-CCR7-) differentiation stage and, for the most part, lose CD28 expression." (PMID 35954341, 2022). "Tumor-infiltrating cells from the IE group showed significantly increased expression of both markers (TGF-β1, p = 0.001 and CTLA-4, p = 0.002)." (PMID 36358618, 2022). "The blockade of CTLA-4 triggered CD28-dependent hyper-proliferation of Tregs in the TME, and the inactivation of accompanied Tregs is required to achieve tumor regression." (PMID 35585567, 2022). "In the tumor microenvironment, the ratio of CD8+ T cells to CD4 + FOXP3+ regulatory T cells was significantly elevated and exhausted CD8+ T cells (PD-1+, CTLA-4+, TIM-3+, or LAG-3+ cells) were significantly reduced in the triple combination group." (PMID 35681672, 2022). "CD8+ T lymphocytes are the primary cytotoxic tumor-infiltrating lymphocyte subset in HCC, and the immune checkpoints PD-1, CTLA-4, and LAG-3 are negative regulators of CTL function." (PMID 35912257, 2022). "Examples are the monoclonal antibodies (mAbs) for programmed cell death 1/ligand 1 (PD-1/PD-L1) and cytotoxic T-lymphocyte antigen 4 (CTLA-4), both of which suppress the cytotoxic effect of CD8 T cells on tumor cells." (PMID 35399527, 2022). "Immune checkpoint proteins such as cytotoxic T lymphocyte antigen 4 (CTLA-4) and programmed death 1 (PD-1)/PD-1 ligand (PD-L1) axis modulate immune responses by negatively regulating T cells; however, this mechanism may impair anti-tumor immune responses in patients with malignancy." (PMID 36341387, 2022). "This resulted in the development of favored anti-tumor response (Th1 differentiation, NK and CD8 + CTL recruitment) and down-regulation of immune suppression signatures (PD-1, CTLA-4, TIM-3)." (PMID 35181743, 2022). "Dual blockade of CD96 with PD-1, PD-L1, TIGIT, or CTLA-4 increases antitumor response, and triple blockade of CD96, PD-1 and TIGIT yields the highest level of antitumoral immunity in various mouse tumor models." (PMID 35164813, 2022). "As a result of the discovery of novel ICIs targeting CTLA4 and PD1, which are generated by activated T cells, neoantigens have emerged as important tumor antigens for the human immune system." (PMID 36620557, 2022). "Core needle or resected tumor biopsies at baseline from primary ICC are referred to as P-ICC, whereas tumor biopsies from ICC samples treated with ICBs (PD-1 or PD-L1/CTLA-4) are denoted as T-ICC." (PMID 35558087, 2022). "CTLA-4 inhibitors (such as ipilimumab and tremelimumab) improve the activity of APC and T lymphocytes to recognize and eliminate tumor cells." (PMID 35075482, 2022). "Tumor-associated macrophages (TAMs) and the surrounding tumor microglia release immunosuppressive and pro-tumorigenic cytokines into the tumor microenvironment, inducing cytotoxic T-cell (CTL) apoptosis mediated by PD-L1, CTLA-4, and FasL." (PMID 35203636, 2022). "We collected 23 tumor cases and evaluated the protein levels of GOLM1, PD-1, PD-L1, CTLA4, and IFN-γ by IHC staining." (PMID 36468024, 2022). "TIM-3, similarly to CTLA-4, belongs to the immunoglobulin superfamily and may exert both inhibitory and co-stimulatory functions in physiological situations, but in the context of cancer, its role in the suppression of anti-tumor responses has been clearly defined." (PMID 35328349, 2022). "Anti-CTLA-4 treatment also led to anincrease in the frequency of effector memory and PD-1+CD8+ T cells in tumours." (PMID 35930804, 2022).
tumor (continued). "There is evidence that blocking the PD-1 pathway alone or in combination with anti-CTLA-4 can produce antitumor effects in NSCLC or SCLC, and combination therapy seems to provide a larger tumor response, but treatment-related toxicity is also increased." (PMID 35159131, 2022). "At present, immune checkpoints including PD-L1, CTLA-4, LAG3, TIGIT and TIM-3, are thought to contribute to tumor immune escape." (PMID 35665772, 2022). "Only two genes, OX40L and CTLA4, had significantly higher protein expression in TAS as compared to tumor (FDR < 0.2 and p-value < 0.05)." (PMID 36230846, 2022). "Anti‐CTLA‐4 antibodies were intravenously injected after RT to block CTLA‐4 on T cells, showing a significant effect in prevention of tumor metastases." (PMID 35652198, 2022). "T cell suppressor receptors such as CTLA-4, PD-1, and TIGIT are essential for T cell activation, antigen recognition, and recruitment, and can inhibit effective anti-tumor immune responses." (PMID 36703779, 2022). "These humanized monoclonal antibodies target inhibitory receptors (CTLA-4, PD-1, LAG-3, TIM-3) and ligands (PD-L1) expressed on T lymphocytes, antigen-presenting cells, and tumor cells, eliciting an anti-tumor response by stimulating the immune system." (PMID 35269781, 2022). "The depletion of the IFNGR1 gene in B16 tumor cells suppressed IFN-γ mediated apoptosis and decreased the antitumor effects of anti-CTLA-4 therapy in a mouse model." (PMID 36189283, 2022). "TGF-β not only contributes to the activation of Tregs and tumor angiogenesis cytokines, but also TGF-β induces upregulation of CTLA-4 expression by Treg." (PMID 35205714, 2022). "In models not including the HPV status, the main predictors of worse OS were positive smoking history, a lower number of parenchymal PD-1+CD8+ T cells, a higher number of all CTLA4+CD8+ T, and tumor size or tumor stage." (PMID 36359314, 2022). "Administration of neutralizing monoclonal antibodies against CTLA4 are able to selectively deplete FOXP3+ Treg cells, and thereby promote tumor immunity by activating effector CD8+ T cells." (PMID 36159789, 2022). "Tregs, denoted by increased expression of Foxp3, Ctla4, and Tnfrsf4 (CD134), represented 4.5% of sensitive tumor T cells compared to half as many (2.3%) in the resistant populations." (PMID 35924165, 2022). "We found that we did achieve more statistical significance, for example CTLA-4 and ICOS were significantly decreased on the surface of tumour-infiltrating CD4+ T cells compared with the treatment-naïve setting." (PMID 35366537, 2022). "Altered-immunosuppressed tumor shows an intermediate degree of T cell and CTL infiltration and immunoscore, T cell checkpoints (PD-1, CTLA-4, TIM3, and LAG3), immune suppressive cells (MDSC and Treg), and inhibitory cytokines (TGF-, IL-10 and VEGF)." (PMID 36293435, 2022). "We also found DC-STAMP expression had a correlation with PDCD1, CD274, CTLA-4, and TIGIT which were exhaustion markers of T cells and considered a dysfunction of anti-tumor immunity." (PMID 35571050, 2022). "The results showed that CTLA4, HAVCR2, PDCD1, PDCD1LG2, and TIGIT significantly differed in tumor tissues and normal tissues." (PMID 36618928, 2022). "SIGLEC15, PDCD1LG2 (PD-L2), TIGIT, PDCD1 (PD-1), CD274 (PD-L1), CTLA4, LAG3, and HAVCR2 (TIM3) are transcripts related to immunological checkpoints that perform a vital function in tumor immune evasion." (PMID 36042287, 2022). "Considering T cell exhaustion, the constructions with anti-CAIX CD28 CAR and anti-PD-L1 secretion and with 4-1BB CAR with or without anti-PD-L1 secretion showed reduced co-expression of PD-1, TIM-3, CTLA-4, and CD39 in viable tumor-infiltrating T cells." (PMID 35628256, 2022). "Consistently, we observed a more distinct immune phenotype at S2 tumours with reduced GZMB (granzyme B) and enriched PDCD1 (PD-1), FOXP3 and CTLA4 compared to N or S1 and S3 tumours." (PMID 35301339, 2022).